ENSG00000207130
Synonyms: LOC124900558
Gene: Small nucleolar RNA gene on chromosome 3 (128,714,571 to 128,714,705, reverse strand). Ensembl gene ENSG00000207130.
Gene Ontology:
Biological process: RNA processing
Cellular component: nucleolus
Homologues: Orthologues: rat LOC120100364 (61% identical), mouse Gm26147 (60% identical). Paralogues in human: SNORA24 (91% identical), SNORA24B (88% identical).